RYR1 (ryanodine receptor 1)
Diseases named in the same sentence as RYR1 in open-access papers (continued):
Sharing a sentence is not in itself a finding about the gene and the disease.
myopathies (continued). "The pathological heterogenicity of RYR1-related myopathy and its relationship with the location of RYR1 variations in our patients were consistent with previous reports." (PMID 35693006, 2022). "Additional studies are needed to further examine the relationship of MANF and RYR1-related myopathies." (PMID 35698232, 2022). "Myopathies (e.g., Duchenne’s muscular dystrophy (DMD), Steinert’s myopathy, diseases related to a mutation in the RYR1 gene, and many others) greatly affect the quality of life and the life expectancy of many patients." (PMID 36297564, 2022). "In the present study, both RyR1-knockdown myoblasts and CRISPR/Cas9-based RyR1-knockout myoblasts were employed to explore the role of RyR1 in myogenic differentiation, myotube formation as well as the potential mechanism of RyR1-related myopathies." (PMID 35144690, 2022). "In this study, we employed CRISPR/Cas9-based RyR1-KO myoblasts and siRNA-mediated RyR1-knockdown myoblasts to explore the role of RyR1 in myogenesis and formation mechanism of RyR1-related myopathies." (PMID 35144690, 2022). "However, the potential pathogenesis of RYR1 mutation-associated myopathies remains largely unknown." (PMID 35692882, 2022). "Clinical and pathological overlaps make the differential diagnosis of RYR1-related myopathies difficult." (PMID 36131268, 2022). "In conclusion, we reported a novel heterozygous RYR1 p.Ser2300Pro variant classified as PS3_Supporting by modified ACMG-AMP criteria, leading to MH accompanied by multi-minicore myopathy." (PMID 36292611, 2022). "In the treatment of RYR1-related myopathies, S107 normalizes an increased calcium leak and activity of calcium-activated proteases." (PMID 35399287, 2022). "If, as we suggest, RyR1 dysfunction initiates the intracellular changes that lead to statin‐induced myopathy, then we would indeed expect the side‐effects of cerivastatin to be the most severe of the clinically relevant statins." (PMID 35703154, 2022). "We report a Korean having MH with multi-minicore myopathy functionally supported by RYR1-mediated intracellular Ca2+ release testing in B lymphocytes." (PMID 36292611, 2022). "We analyzed the data of 33 patients with RYR1-related myopathy, attempting to elucidate correlations between phenotype, genotype, and protein structure of RyR1." (PMID 35693006, 2022). "SEPN1-RM predominantly manifests as cervico-dorsal spinal rigidity that differs from the rigid spine in myopathies caused by mutations in LMNA, EMD, COL6 (Bönnemann, 2011), or RYR1." (PMID 35368679, 2022). "Though transgenic mouse model of RYR1- related myopathy has been successfully constructed for more than 10 years." (PMID 35693006, 2022). "Clinical diversity of RYR1-related myopathy was impacted by the inheritance mode, variation type, and variant location." (PMID 35693006, 2022). "Several FDA-approved inhibitors of p38 MAPK were identified as potential therapeutic candidates for RYR1-related myopathies using a multi-species discovery pipeline." (PMID 34768808, 2021). "An in vitro study that garnered good results included exon skipping to remove a pseudo-exon from the mRNA of a child with a recessive RYR1-related myopathy." (PMID 34827576, 2021). "In five patients, additional core‐like structures, which are a common feature in RYR1‐related myopathies, were observed in the muscle biopsies." (PMID 34463354, 2021). "Due to the preliminary pathology findings of myopathy, RYR1 (ab2868) antibody immunohistochemical staining was pursued to investigate the abnormalities in RYR1 density, location, and structure in the patient's muscle biopsy." (PMID 34528764, 2021). "Defects in redox homeostasis have also been described in SEPN1-related myopathy, an inherited muscle disease caused by mutations in gene encoding selenoprotein-N (SELENON), which displays clinical and pathological overlap with RYR1-related myopathies." (PMID 34205993, 2021).
myopathies (continued). "While myopathy leading to congenital hypotonia and respiratory insufficiency is a well‐known phenotype of the autosomal recessive form of RYR1‐RM, it is less clear how other aspects of the patient's phenotype relate to the genotype." (PMID 34528764, 2021). "A mouse model mimicking recessive cases of RYR1-related myopathy with early clinical onset was generated using the CRISPR/Cas9 gene-editing strategy." (PMID 34768808, 2021). "A comprehensive review of the different preclinical models available for RYR1-related myopathies was recently published." (PMID 34768808, 2021). "Since then, RYR1-related myopathies (RYR1-RM) have been described as rare, histopathologically and clinically heterogeneous, and slowly progressive neuromuscular disorders." (PMID 33190635, 2020). "We present here the first model of mice with a clear myopathy phenotype due to the exclusive reduction in the expression of the RYR1 gene." (PMID 33176865, 2020). "So far, none of these methods has been successful in discovering treatments for RYR1-related myopathies." (PMID 32223895, 2020). "The high incidence of RYR1 mutations in CMs and the variable, even non neuromuscular, manifestations, called for the need of the 217th ENMC international workshop, which was dedicated to recent advances in the field of RYR1-related myopathies." (PMID 32456280, 2020). "Analogical results have been gained in a disease model of selenoprotein N-related myopathy (SELENON-myopathy), a clinical heterogenous muscle disease that shares common features with RYR1-myopathy." (PMID 32823799, 2020). "RYR1 and TTN therefore clearly benefit from high throughput technologies such as NGS and are proving to be a major cause in myopathies." (PMID 32403337, 2020). "With the continuing emergence of new clinical subtypes along the RYR1 disease spectrum and reports of adult-onset phenotypes, nuanced nomenclatures have been reported (RYR1- [related, related congenital, congenital] myopathies)." (PMID 33190635, 2020). "Accordingly, variable penetrance and phenotypic expression have been reported for RYR1-related myopathies." (PMID 31165076, 2019). "Whilst the Ryr1TM/Inde and Ryr1Q1970fsX16/A4329D lines are interesting new models that fill an unmet need to study severe recessive RYR1-related core myopathies, the mechanisms of disease progression are yet to be determined." (PMID 31874912, 2019). "Dusty cores represent the most frequent histopathological manifestation of RYR1-recessive myopathies." (PMID 30611313, 2019). "In conclusion, DuCD is the most frequent histopathological presentation of RYR1-recessive myopathies." (PMID 30611313, 2019). "Here we report two Italian families, one with myopathy and another with CCD, associated with RYR1 variants and RYR1 unbalanced expression in lymphoblastoid cells." (PMID 31165076, 2019). "Patient 522 has clear signs of myopathy and a clinical picture milder than that of patients 425 and 521, who are composite heterozygous for RYR1 c.9293G>T (p.S3098I) and c.14771_14772insTAGACAGGGTGTTGCTCTGTTGCCCTTCTT (p.F4924_V4925insRQGVALLPFF)." (PMID 31165076, 2019). "Previously reported cases of MmD in RYR1-recessive myopathies, had very similar oxidative stains to those observed in DuCD." (PMID 30611313, 2019). "Although several candidate pathways are activated in patient biopsies, to our knowledge the only therapeutic intervention tested in human cells is targeting ROS with NAC, which has led to a clinical trial in RYR1-related myopathy (NCT02362425)." (PMID 31874912, 2019). "The demonstration that the kinetic properties of the RyR1 channel are altered in MHS or in myopathic patients implicates the mutated channel in the pathogenesis of MHS and myopathies." (PMID 31165076, 2019). "The prevalence of RYR1-related core myopathies has been difficult to ascertain due to the wide range of causative mutations and clinical manifestations." (PMID 31874912, 2019).
myopathies (continued). "Taken together, the Ryr1I4895T/+, Ryr1Y522S/+, Ryr1R163C, Ryr1Q1970fsX16/A4329D and Ryr1TM/Inde mice show striking phenotypic similarities to the histopathology, Ca2+ transients, ECC and muscle weakness of RYR1-related core myopathy patients." (PMID 31874912, 2019). "Two new models of recessive RYR1-related myopathies have recently been developed that aim to recapitulate the severe pediatric phenotypes of a subset of RYR1-related core myopathy patients." (PMID 31874912, 2019). "In conclusion, dusty core is the most frequent histopathological presentation of RYR1-recessive myopathies." (PMID 30611313, 2019). "Progression of muscle pathology, which has been noted in RYR1-related myopathies but also in one MH pedigree where muscle biopsies were performed at different ages, was observed in two of the three patients in whom subsequent biopsies had been performed." (PMID 30788618, 2019). "The inheritance of RYR1-related myopathies is complex, and, moreover, a high phenotypic variability is associated with some RYR1 SVs, even in patients of the same family with the same SV and in the same individual at different ages." (PMID 31165076, 2019). "A critical aspect for modeling core myopathies is the formation of mature SR and T-tubules with RYR1-DHPR clustering." (PMID 31874912, 2019). "Of all CM, ryanodine receptor 1-related myopathies (RYR1-RM), with an estimated US pediatric point prevalence of at least 1:90,000, are recognized as the most frequently diagnosed." (PMID 30406384, 2018). "Further analysis of promoters of de-regulated genes also indicated a set of key transcription factors (TFs) responsible for the altered gene expression profile in human patients and animal models of RyR1-related core myopathies (Data Set S3)." (PMID 29701772, 2018). "Mild bilateral ptosis with a complex ophthalmoplegia most marked on upgaze, a typical finding in recessive RYR1-related myopathies, was noted." (PMID 29298851, 2018). "The dominant form of RyR1 myopathies manifests clinically due to a leaky RyR1 channel, which results in excessive skeletal muscle Ca++." (PMID 27855725, 2016). "At that time, the possibility of a core myopathy prompted us to analyze RYR1 and we detected a heterozygous c.880G > A:p.(Glu294Lys)." (PMID 27005958, 2016). "Here, the results indicate that LMPS can be considered as the extreme end of the RYR1-related neonatal myopathy spectrum." (PMID 26932181, 2016). "Future research in RyR1 myopathies should not only observe Ca++ regulation with different RyR1 mutations but also NOS activity and localization, NO levels, CaM levels and CaM-bound NOS together." (PMID 27855725, 2016). "Similar alterations were described previously in biopsies from patients diagnosed with CCD and in RYR1 knock-in mouse models of core myopathy." (PMID 26075051, 2015). "Skeletal muscle research will continue to expand our understanding of these myopathies, as well as the function and dysfunction of the RyR1." (PMID 26793121, 2015). "There are several human and animal myopathies that involve disturbances in the regulation of skeletal muscle calcium homeostasis and hypersensitivity to agents that influence RYR1 channel opening, in particular, caffeine and halothane." (PMID 25148524, 2014). "A mutation in RyR1 associated with malignant hyperthermia increases susceptibility to an adverse response to simvastatin due to enhanced Ca2+ release from the sarcoplasmic reticulum, suggesting that RyR1 mutations may underlie enhanced susceptibility to statin-induced myopathies." (PMID 24004537, 2013). "This would be consistent with animal model data, particularly from the zebrafish model of RYR1-myopathy, which has severely reduced expression (>90% reduction), obvious myopathic features, but no central cores and very few true minicores." (PMID 23919265, 2013).
myopathies (continued). "In particular, we highlight the MH/CCD hotpspot regions, (and the selectivity filter that lies within hotspot region 3), as likely to be important in the pathogenesis of many recessive RYR1-related myopathies." (PMID 23919265, 2013). "MT, CB, LM, DM, JC, JRD, and GW provided new cases of RYR1 myopathy and also provided critical reading of the manuscript." (PMID 23919265, 2013). "In some recessive RYR1 myopathies, an alteration of the RyR1 protein level has been reported in the skeletal muscles." (PMID 23894444, 2013). "We suggest that RYR1 related myopathy should be considered in a wide variety of clinical and pathological presentation in childhood myopathies." (PMID 23894444, 2013). "Many patients with autosomal recessive RYR1 related myopathies described in the literature have a genetic background characterized by compound heterozygous mutations, more specifically a missense mutation on one allele and a null mutation on the other." (PMID 23894444, 2013). "Both SEPN1 and RYR1 were excluded, as were ACTA1 and TPM3, in which mutations cause congenital fiber type disproportion, a myopathy clinically similar to MmD." (PMID 22371254, 2012). "We show that successful application of ASGS for therapeutic benefit in a RyR1-related myopathy requires the siRNA to be capable of preferentially silencing the mutant allele." (PMID 23152933, 2012). "In that study, tissue-specific mono-allelic RYR1 expression was observed in a group of CCD patients with recessive core myopathies." (PMID 20482855, 2010). "Exercise capacity testing may be informative for individualizing exercise regimens for persons with RYR1-related myopathies." (PMID 40993798, 2025). "However, a significant decrease in RyR1 protein levels was also found in muscle samples of patients with inflammatory myopathies." (PMID 40943287, 2025). "Ambulatory individuals (32 adults, 16 children) with genetically confirmed RYR1-related myopathies performed exercise testing on a cycle ergometer and a six-minute walk test at baseline and month six (pre-intervention phase) of a randomized controlled trial (NCT02362425)." (PMID 40993798, 2025). "However, paralogs of myopathy genes are often expressed in different tissues, such as RYR1 and CASQ1, which are expressed in skeletal muscles, whereas RYR2 and CASQ2 are expressed in cardiac muscles." (PMID 39945189, 2025). "Pathogenic variations affecting the ryanodine receptor 1 (RYR1) gene may result in a variety of neuromuscular disorders, collectively known as RYR1-related myopathies." (PMID 40993798, 2025). "These myopathies, which may show dominant or recessive inheritance patterns, are collectively known as RYR1-related myopathies (RYR1-RM)." (PMID 41373610, 2025). "This also suggests that exercise guidance may become a pivotal component of future clinical care guidelines for RYR1-related myopathies." (PMID 39108538, 2024). "Therefore, the term “RYR1-related myopathies” was introduced instead, and some authors even suggested the term “RYR1-related disorders” to best cover the broad spectrum." (PMID 39409197, 2024). "MYH1, a cytoskeletal muscular protein interacting with actin, has not been clearly associated with RYR1-related myopathies." (PMID 39273074, 2024). "However, RYR1-related myopathies comprise a highly heterogeneous group of muscular disorders, ranging from malignant hyperthermia (MH) without clinically evident muscular disease to severe congenital muscular myopathy, sometimes even fatal." (PMID 39409197, 2024). "The authors discuss that both the heart defect and the intracerebral bleeding could be independent from the RYR1-related myopathy, but may also constitute very rare manifestations of the RYR1-associated spectrum." (PMID 39409197, 2024).
myopathies (continued). "Conversely, MRI features helping differentiating between these two genotypes include the relative higher degree of involvement of the biceps femoris, tibialis anterior and tibialis posterior muscles in the TPM3‐NM cohort versus the typical sparing of these muscles in RYR1 myopathy." (PMID 37265148, 2023). "Different RYR1 mutations can lead to channel loss of function (myopathy without MH) or channel gain of function (isolated MH or MH with associated myopathy), and both dominant and recessive inheritances have been described." (PMID 37510264, 2023). "Whereas MH patients do not have any phenotype without anesthesia, almost 260 RyR1 mutations are associated with various myopathies (such as CCD and MMD), which are often characterized by hypotonia and proximal muscle weakness." (PMID 36982484, 2023). "These histological alterations, although variable, may represent mild features that, in RYR1-related myopathies, evolve to more severe histological and structural alterations." (PMID 35980353, 2022). "We previously demonstrated that simvastatin activates skeletal ryanodine receptors (RyR1), an effect that could be important in initiating myopathy." (PMID 35703154, 2022). "A total of 33 patients (18 male, 15 female) with RYR1-related myopathy were recruited." (PMID 35693006, 2022). "Diagnosis of RYR1 mutation-associated myopathies is delayed and difficult when there are no clear histopathological features." (PMID 35692882, 2022). "Of note, comparison of RNAseq data to age/sex matched TA muscle from another mouse with severe myopathy, a model of recessive RYR1 related myopathy, shows completely different transcriptomic signatures, supporting the specificity of PKC hyperactivation in Mtm1 KO muscle." (PMID 35844027, 2022). "In our series, a predicted altered quantitative level of RyR1 is consistent with stable or slowly progressive mild/moderate myopathy, suggesting that the level of RyR1 protein may be critical for the normal excitation–contraction coupling." (PMID 35428369, 2022). "The core myopathies are genetically heterogeneous and histopathology may suggest the underlying gene defect only in CCD, mostly due to the ryanodine receptor 1 gene (RYR1), and DuCD due to biallelic RYR1 mutations." (PMID 35428369, 2022). "The relationship between phenotype and genotype of RYR1-related myopathies is complex and unclear." (PMID 35693006, 2022). "RYR1 mutation-associated myopathies is considered the most common nondystrophic muscle disease in humans, with an estimated prevalence of 1/400 in an exome analysis from 870 individuals." (PMID 35692882, 2022). "First, we reported 18 novel variations in 6 myopathy-causing genes, including RYR1, NEB, ACTA1, DNM2, TTN and TNNT1, and we described the clinical discrepancy between our patients and previous reports, especially in RYR1- and TNNT1- related myopathy." (PMID 35081925, 2022). "Interestingly, multi-minicore myopathy was observed in muscle biopsies by SDH histochemical staining in our dominant RYR1-related case." (PMID 36292611, 2022). "As reported by existing genetic studies conducted in numerous patients with myopathy, RYR1 variation has been most commonly reported to lead to congenital myopathy including central nuclear myopathy (CNM), congenital fibrous type disorder, and multi-micronucleus disease (MmD)." (PMID 35692882, 2022). "Patients with inherited mutations in RyR1 may exhibit muscle weakness as part of a heterogeneous, complex disorder known as RYR1-related myopathy (RYR1-RM) or more recently termed RYR1-related disorders (RYR1-RD)." (PMID 34809703, 2021). "Finally, nine rare PTVs in the ACMG59 genes were harbored by 14 carriers, two of which displayed expected phenotypes: myopathy (frameshift deletion in RYR1) and prolonged QTc interval (frameshift insertion in KCNQ1)." (PMID 34691145, 2021).